PRL (prolactin)
Diseases named in the same sentence as PRL in open-access papers (continued):
Sharing a sentence is not in itself a finding about the gene and the disease.
breast cancer (continued). "However, the very similar associations between prolactin and breast cancer risk observed in our previous study of invasive disease and the current study of in situ disease suggest that circulating prolactin may influence risk of invasive and in situ breast cancer via the same aetiological pathway." (PMID 25887963, 2015). "In contrast to the modest PRL-induced increase in growth of breast cancer cells cultured on tissue culture plastic, PRL alone did not significantly increase growth of either MCF-7 or T47D cells in the 3D collagen-I matrices." (PMID 25607819, 2015). "Others have reported that PRL also antagonizes traditional chemotherapies in breast cancer cells in vitro." (PMID 25607819, 2015). "On the other hand, it has been reported that PRL stimuli prevents apoptosis after treatment with C2-ceramide in the breast cancer cell lines T-47D, MCF-7 and Hs578T." (PMID 26346346, 2015). "PRL has been shown to cooperate with estrogen in 2-dimensional cultures of breast cancer cell lines." (PMID 25607819, 2015). "Although interactions between the ECM and PRL/PRLR signals in breast cancer have been examined, the current studies revealed striking effects of the combination of PRL and estrogen in a high density/ stiff ECM that were not apparent with either hormone alone." (PMID 25607819, 2015). "T47D and MCF-7 cells are two of the most studied ERα+/PRLR+ luminal breast cancer cell lines with respect to both estrogen and PRL actions." (PMID 25607819, 2015). "Our studies demonstrate the power of matrix density to determine the outcomes of hormone actions and suggest that stiff matrices are potent collaborators of estrogen and PRL in progression of ERα+ breast cancer." (PMID 25607819, 2015). "Using 3D culture in collagen-I matrices, we previously demonstrated marked effects of ECM stiffness on the spectrum of PRL-induced signals and behavioral outcomes in luminal breast cancer cells." (PMID 25607819, 2015). "While the JAK2/STAT5 cascade is the major physiological pathway for PRL actions in mammary function, SFKs mediate many PRL signals in breast cancer." (PMID 25607819, 2015). "In summary, we have shown that high density/ stiff collagen matrices enhance pro-tumorigenic crosstalk between estrogen and PRL in ERα+/PRLR+ luminal breast cancer cells." (PMID 25607819, 2015). "In particular, prolactin contributes to metastasis and worse survival preventing apoptosis and promoting cell motility and angiogenesis in breast cancer." (PMID 25875532, 2015). "While first identified as the key hormone mediating growth and differentiation of mammary epithelium and lactation, PRL has recently gained attention for its role in the development of breast cancer." (PMID 26733941, 2015). "Our studies demonstrate the power of matrix density to regulate the outcomes of hormone actions, and identify high density/ stiff matrices as critical collaborators of estrogen and PRL to drive progression of ERα+ breast cancer." (PMID 25607819, 2015). "The phosphorylation of STAT5 in mammary epithelium is driven almost completely by prolactin, and prolactin promotes survival and proliferation of mammary epithelium, two key properties of breast cancer." (PMID 24762632, 2014). "We have previously shown that PRL activates the AMPK pathway in an LKB1-dependent manner in specific human breast cancer cell lines, most notably MDA-MB-231 cells." (PMID 24913037, 2014). "The potential relationship between breast cancer subgroups and prolactin will however need to be studied in experimental studies, in order to investigate this further." (PMID 24708573, 2014). "A similar time frame has been described for assessing STAT5A-mediated reporter gene activity of other promoters in breast cancer cells stimulated with a similar concentration of PRL." (PMID 24913037, 2014). "With some controversy prolactin (PRL) has been proposed as a key player in the development of mammary cancer in rodent models." (PMID 25136563, 2014).
breast cancer (continued). "Circulating levels of estrogen and progesterone are at their highest during pregnancy, while the levels of prolactin, a potent mitogen for breast cancer cells, are at their peak during pregnancy and lactation." (PMID 24405573, 2014). "This study offers mechanistically rational basis for invasiveness fueled by prolactin in refractory states to adjuvant therapies in breast cancer." (PMID 25193864, 2014). "LKB1 is differentially regulated by PRL at the level of transcription in representative human breast cancer cells." (PMID 24913037, 2014). "Prolactin (PRL) and Signal transducer and activator of transcription (STAT) proteins have been associated with breast cancer progression." (PMID 24913037, 2014). "A previous report showed that prolactin-induced ERK activation is dependent on Rac1 in breast cancer cells." (PMID 25121739, 2014). "Interestingly, in I rats, serum PRL was significantly higher in those rats that developed tumors, suggesting that supraphysiological levels of PRL may be relevant in increasing the risk of mammary cancer." (PMID 25136563, 2014). "This demonstrates the relevance of the endogenous levels of PRL in the up-regulation of PRLR observed in mammary tumors." (PMID 25193864, 2014). "Our studies have shown that prolactin produced in breast cancer cells through intracrine activation of PRLR and via at least two signal transduction pathways, JAK2/STAT5 and JAK2/PI3K/MEK/ERK, up-regulates the human prolactin receptor." (PMID 25193864, 2014). "Prolactin (PRL) serves a critical role in breast cancer progression via activation of its cognate receptor." (PMID 25193864, 2014). "Future studies to identify the mechanism of activation of Jak1 by PRL receptors in breast cancer and the effect of Jak1-activation on PRL-modulated biology of breast cancer are now warranted." (PMID 23758962, 2013). "Several studies have identified genes regulated by PRL in the normal mouse mammary gland, but only a limited number of studies have been carried out in human breast cancer cells." (PMID 23758962, 2013). "Although the major association of PRL with human cancer is given in breast cancer; the role of PRL in the proliferation of classical breast cancer cell lines is controversial." (PMID 24148306, 2013). "Similar dose response analyzes with PRL and blocking antibodies were performed in breast cancer and HaCat cells, observing an increase of 6% in the cell number of T47-D after 3 days of incubation with PRL." (PMID 24148306, 2013). "The pathophysiological relevance of potent and reversible acidosis-disruption of prolactin signaling in breast cancer is supported by extensive experimental evidence and correlative studies in archival human breast cancer specimens provided clinical relevance." (PMID 24004716, 2013). "The present study reports a novel panel of PRL-modulated transcripts based on analysis of human breast cancer xenograft tumors in vivo." (PMID 23758962, 2013). "A retrospective study of the serum hormone levels of FSH, LH, P and PRL and the expression status of Her-2 and Ki67 was performed using 187 post-menopausal females with breast cancer." (PMID 24137476, 2013). "The present study aimed to shed new light on how PRL modulates estrogen receptor (ER)-positive breast cancer through global transcript profiling of a human breast cancer xenograft model in vivo." (PMID 23758962, 2013). "Prolactin responsiveness of five human breast cancer cell lines, including ER-positive T47D, MCF7 and BT474 and ER-negative SKBR3 and MDA-MB-468, was analyzed at pHe of 6.8 and at normal tissue pHe of 7.4." (PMID 24004716, 2013). "Together, these data established that prolactin signaling in human breast cancer cells is highly sensitive to extracellular acidosis even at high prolactin concentrations and for extended periods." (PMID 24004716, 2013).
breast cancer (continued). "The instructive role of hormone-sensing cells in premalignant development suggests targeting Wip1 or prolactin signaling as an orthogonal strategy for inhibiting breast cancer development or relapse." (PMID 23369183, 2013). "In vivo, PRL over-expressing transgenic mice have an increased incidence of mammary tumors, while PRL knock-out mice have a reduced incidence of mammary tumors." (PMID 23758962, 2013). "The role of PRL in tumorigenesis was suggested some decades ago in breast cancer, mainly in animal-based research." (PMID 24148306, 2013). "The present study is the first to report a panel of PRL-modulated transcripts based on global transcript profiling of human breast cancer xenotransplant tumors in vivo." (PMID 23758962, 2013). "On the other hand, evidence suggests that PRL acts to preserve cellular differentiation of breast cancer." (PMID 23758962, 2013). "Jak1 was reported to be activated by PRL signaling in human breast cancer lines and cooperate with Jak2 to enhance signaling pathways downstream of PRL receptors, including Stat5, Stat3 and Erk activation." (PMID 23758962, 2013). "In breast cancer cells and Nb2 cells, PRL stimulates ERK1/2 phosphorylation in the mitogen-activated protein (MAP) kinase pathway, which appears to mediate the effects of PRL on cell proliferation." (PMID 23317095, 2013). "We conclude that prolactin-induced Stat5 activation in human breast cancer cell lines is highly sensitive to moderate pH reduction." (PMID 24004716, 2013). "The present study reports a panel of 130 PRL regulated transcripts in the human T47D breast cancer xenotransplant model in estrogenized nude mice." (PMID 23758962, 2013). "In the present study, which focused on PRL-modulated transcripts in the T47D breast cancer model, experimental overexpression of Stat5a or Stat5b enhanced to a comparable extent PRL-modulation of most transcripts tested." (PMID 23758962, 2013). "SKBR3 and T47D breast cancer cell lines were stimulated with prolactin concentrations ranging from 1 to 100 nM for 15 min at different pHe." (PMID 24004716, 2013). "In breast cancer cells, PRL activates Jak2, stimulates phosphorylation of Stat1, Stat3 and Stat5 and induces cell proliferation." (PMID 23317095, 2013). "Consistent with PRL-enhancement of E2-driven proliferation of breast cancer cells, select PRL-modulated transcripts displayed positive co-regulation by E2, including the growth factors EREG and AREG." (PMID 23758962, 2013). "From this panel of 130 PRL-modulated transcripts, a subset of 18 transcripts with established breast cancer-relevance was selected for further analysis and validation." (PMID 23758962, 2013). "The interconnection between the different signaling pathways of PRL can increase the proliferation, survival, cell migration and invasion of breast cancer and is responsible for mediating antiapoptotic and proliferative effects of PRL." (PMID 23317095, 2013). "The prolactin-responsive human T47D breast cancer cell line was xenotransplanted into nude mice and global transcript profiling was carried out following treatment with or without human PRL for 48 h." (PMID 23758962, 2013). "Collectively, the validation studies support the value of the transcript data and are expected to facilitate better understanding of PRL action in breast cancer." (PMID 23758962, 2013). "In breast cancer cells PRL confers resistance against cisplatin by activating a detoxification enzyme and in ovarian carcinoma cells PRL and its receptor inhibit apoptosis induced by serum starvation or cisplatin treatment." (PMID 24257371, 2013). "Based on in vitro and in vivo experimental approaches and extensive quantitative in situ analyses of human breast cancer specimens, we now demonstrate that prolactin activation of prolactin receptors is selectively disrupted even at mildly acidic pHe of 6.8." (PMID 24004716, 2013).
breast cancer (continued). "We next characterized the proton concentration-dependence of prolactin-responsiveness of breast cancer cells by analyzing prolactin-induced phosphorylation of Stat5 and Erk over a pathophysiological pHe range from 7.4 to 6.6." (PMID 24004716, 2013). "PRL activates multiple signaling pathways in breast cancer cells, with Stat5 constituting a principal mediator of PRL actions during development and differentiation of the mammary gland." (PMID 23758962, 2013). "Our results are consistent with a role of PRL in reducing the tumor-initiating CK5-positive cell population, which is implicated in breast cancer metastasis and relapse." (PMID 23758962, 2013). "Possible proliferative, anti-apoptotic, migratory and angiogenic effects of PRL on human mammary cancer cells in vitro and in vivo were suggested." (PMID 22647582, 2012). "Even a very low expression level of the receptor is sufficient to mediate PRL responsiveness in human breast cancer cell lines." (PMID 22647582, 2012). "The importance of PRL for canine mammary tumor development remains to be elucidated, and future studies are of interest." (PMID 22647582, 2012). "Recently, the promoting role of prolactin (PRL) in the development of human breast carcinoma has been shown." (PMID 22647582, 2012). "Coupled with the enzyme activity data, PRL restored total LKB1 protein levels in both LKB1 siRNA-transfected breast cancer cell lines." (PMID 21294903, 2011). "We found limited evidence for a relationship between common genetic variants in PRL or PRLR and breast cancer." (PMID 21470416, 2011). "We examined the association between SNPs in PRL and PRLR and breast cancer risk in a population of Polish women." (PMID 21470416, 2011). "MCF-7 and MDA-MB-231 breast cancer cells and 184B5 normal breast epithelial cells treated with 100 ng/ml of PRL for 24 hr were used as in vitro models." (PMID 21294903, 2011). "The existence of a functional autocrine/paracrine loop in the breast is further supported by the finding that breast cancer cell growth and survival in the presence of PRL blocking antibodies and antagonists are abrogated." (PMID 21294903, 2011). "In contrast, CPT1 enzyme activity was significantly enhanced in MDA-MB-231 breast cancer cells at both the 100 and 500 ng/ml doses of PRL, resulting in 21.2% and 18.8% increases, respectively, compared to untreated cells (p < 0.02)." (PMID 21294903, 2011). "Epidemiological studies suggest that prolactin (PRL) plays a role in the progression of breast cancer." (PMID 21294903, 2011). "Recent studies suggest that PRL also can antagonize traditional chemotherapeutics in breast cancer cells in vitro, which is supported by small studies of PRL on therapeutic resistance in vivo." (PMID 21276249, 2011). "While a growing number of epidemiological studies suggest that PRL contributes to the progression of breast cancer, clinical trials with dopamine agonists (bromocriptine) targeting pituitary-derived PRL in serum failed to block cancer progression." (PMID 21294903, 2011). "It will be of considerable interest to evaluate the contribution of PPARα on changes in CPT1A expression and activity in breast cancer cells in response to PRL in future studies." (PMID 21294903, 2011). "Although epidemiological data support a role for PRL in the development and progression of breast cancer, relatively little is known about its contributions to this disease." (PMID 21276249, 2011). "To follow up our previous finding of a relationship between serum prolactin and breast cancer risk, we investigated the association between common genetic variation in PRL and PRLR and breast cancer risk in the Polish Breast Cancer Study." (PMID 21470416, 2011). "We examined the association between variant alleles in 25 SNPs - 7 PRL and 18 PRLR - and breast cancer risk." (PMID 21470416, 2011). "It is also involved in several cancers, including breast cancer and prolactin-secreting pituitary adenoma." (PMID 22084690, 2011).
breast cancer (continued). "Our studies demonstrate that prolactin can promote diverse carcinomas in mice, many of which resemble luminal breast cancers, providing a novel experimental model to examine the pathogenesis, progression and treatment responsiveness of this tumor subtype." (PMID 21276249, 2011). "Several breast cancer risk factors have been reported to be associated with prolactin levels, and estrogen has been shown to stimulate the PRL extrapituitary promoter in breast cancer cell lines." (PMID 21470416, 2011). "PRL partially restored CPT1 activity in breast cancer cells in which CPT1A, LKB1, or AMPKα-1 were knocked down." (PMID 21294903, 2011). "Our studies demonstrate that PRL can promote diverse tumor phenotypes, many of which display molecular features of luminal breast cancers, providing insight into the pathogenesis of this cancer subtype." (PMID 21276249, 2011). "PRL also imparts a partial recovery of CPT1 enzyme activity in breast cancer cells in which AMPKα-1 is transiently knocked down, indicating that PRL-mediated AMPK activation contributes to the changes in CPT1 enzyme activity reported here." (PMID 21294903, 2011). "We propose a mechanism by which PRL elicits its effect on CPT1A in representative breast cancer cells." (PMID 21294903, 2011). "This notion is supported by the finding that PRL increases total LKB1 protein levels in breast cancer cells in which LKB1 is transiently knocked down, most notably in MDA-MB-231 cells." (PMID 21294903, 2011). "Previous prospective studies have found an association between prolactin (PRL) levels and increased risk of breast cancer." (PMID 20736944, 2010). "PRL, acting through is receptors, has definitively been shown to increase cell proliferation and decrease apoptosis in breast cancer cells in culture." (PMID 21144038, 2010). "Recent evidence has clearly indicated that PRL plays a role in human breast cancer and hence the receptors for this important hormone should also be assessed in all breast cancer cases." (PMID 21144038, 2010). "Pituitary prolactin levels are known to be increased due to exposure to exogenous estrogens, promote mammary cancer in rats and mice and can activate Ras in rat lymphoma cells with recent studies linking circulating levels to breast cancer." (PMID 20809984, 2010). "More recently, we showed that goserelin administration produces the regression of NMU-induced mammary tumors through the inhibition of prolactin (PRL), tumor necrosis factor (TNF)-alpha and nitric oxide expression." (PMID 19491505, 2009). "Prolactin is recognized as a breast cancer cell survival factor and prolactin inhibitors demonstrate the ability to inhibit cell proliferation in vitro and to slow tumor growth in mice." (PMID 19146682, 2009). "Doxorubicin accordingly induced expression of prolactin mRNA and protein in all five breast cancer cell lines tested." (PMID 18681966, 2008). "This suggests the presence of a clonogenic population of breast cancer cells that are preferentially sensitive to prolactin inhibition." (PMID 18681966, 2008). "Autocrine prolactin appears to act as an inducible survival factor in a clonogenic subpopulation of breast cancer cells." (PMID 18681966, 2008). "Despite these observations, attempts to treat advanced breast cancer through the pharmacological inhibition of pituitary prolactin secretion, either as monotherapy or in combination with tamoxifen, have been disappointing." (PMID 18681966, 2008). "A prolactin excess reduces the tumour latency and increases the tumour incidence and growth rate in multiple rodent models of spontaneous and carcinogen-induced mammary tumours." (PMID 18681966, 2008). "Approaches to antagonise autocrine prolactin in breast cancer cell lines have centred on prolactin-neutralising antibodies and PRLR antagonists." (PMID 18681966, 2008).